SNORD116-8 (small nucleolar RNA, C/D box 116-8)
Synonyms: HBII-85-8
Gene: Small nucleolar RNA gene on chromosome 15 (25,070,432 to 25,070,526, forward strand). Ensembl gene ENSG00000207093.
Gene Ontology:
Biological process: RNA processing
Cellular component: nucleolus
Homologues: Orthologues: macaque SNORD116 (99% identical), rabbit SNORD116 (91% identical), rabbit SNORD116 (89% identical), rabbit SNORD116 (88% identical), rabbit SNORD116 (87% identical), rabbit SNORD116 (84% identical), rabbit SNORD116 (79% identical), rabbit SNORD116 (77% identical), rabbit SNORD116 (76% identical). Paralogues in human: SNORD116-3 (98% identical), SNORD116-9 (98% identical), SNORD116-4 (97% identical), SNORD116-5 (97% identical), SNORD116-6 (97% identical), SNORD116-7 (97% identical), SNORD116-2 (96% identical), SNORD116-1 (95% identical), SNORD116-14 (86% identical), SNORD116-17 (85% identical), SNORD116-19 (85% identical), SNORD116-21 (85% identical), and 20 more.